TIGD1 (tigger transposable element derived 1)
Synonyms: EEYORE
Tractability: PROTAC: ubiquitination databases record sites on it.
Gene: Protein-coding gene on chromosome 2 (232,543,883 to 232,550,557, reverse strand). Ensembl gene ENSG00000221944.
Subcellular location: Nucleus
Subcellular location (Human Protein Atlas): Mitotic chromosome; Nucleoli rim; Nuclear bodies; Nucleoplasm
Gene Ontology:
Molecular function: protein binding; DNA binding; nucleic acid binding
Cellular component: nucleus
Genetic constraint (gnomAD): Loss-of-function variants: 4 observed, 3.32 expected, observed/expected ratio (o/e) 1.21, 90% interval 0.55 to 1.89. That is too few expected variants to judge how well the gene tolerates losing a copy. Missense variants: 43 observed, 42.38 expected, observed/expected ratio (o/e) 1.01, 90% interval 0.79 to 1.31. Synonymous variants: 18 observed, 13.02 expected, observed/expected ratio (o/e) 1.38, 90% interval 0.95 to 1.88.
Homologues: Orthologues: chimpanzee TIGD1 (99% identical), macaque TIGD1 (96% identical), zebrafish si:rp71-1d10.8 (21% identical), tropical clawed frog tigd3 (14% identical), tropical clawed frog XB5896327 (3% identical). Paralogues in human: TIGD2 (25% identical), JRKL (24% identical), TIGD7 (24% identical), JRK (22% identical), TIGD5 (22% identical), TIGD6 (22% identical), TIGD4 (19% identical), CENPB (18% identical), POGZ (17% identical), TIGD3 (15% identical), POGK (14% identical).
Diseases named in the same sentence as TIGD1 in open-access papers:
TIGD1 is named in the same sentence as 40 diseases in open-access papers, as found by Europe PMC text mining. Sharing a sentence is not in itself a finding about the gene and the disease. The quoted sentences say what the papers report.
colorectal cancer (4 papers, 2023 to 2025). A primary or metastatic malignant neoplasm that affects the colon or rectum. "Furthermore, another study has observed that TIGD1 can potentially augment cell death caused by copper toxicity in colorectal cancer cells, by elevating the concentrations of Cu ions." (PMID 38651061, 2024). "The validation of these findings in colon cancer cell lines further underscores TIGD1 as a significant prognostic factor and potential therapeutic target in colorectal cancer." (PMID 40565566, 2025). "Prognosis analyses identified a correlation between elevated TIGD1 expression and shorter survival in liver hepatocellular carcinoma, colon adenocarcinoma, and the colorectal cancer cohort, reinforcing its pro-tumorigenic role in gastrointestinal cancers." (PMID 40565566, 2025). "Researchers have discovered that TIGD1 plays a role in the onset and progression of tumors like colorectal cancer and oral cancer." (PMID 38651061, 2024). "A recent study found that knockdown of TIGD1 was effective in accelerating copper death in colorectal cancer cells induced by the copper death inducer elesclomol, and thus TIGD1 could serve as a key protein in regulating copper-dependent cell death." (PMID 37441804, 2023).
colon cancer (3 papers, 2023 to 2025). "Previous studies have linked TIGD1 to resistance in ovarian and colon cancers, further supporting its role as a potential molecular target for overcoming therapeutic resistance." (PMID 40565566, 2025). "The observed upregulation of TIGD1 in multiple malignancies, particularly in colon cancers, suggests a plausible oncogenic role, as evidenced by its correlation with poor patient prognosis." (PMID 40565566, 2025). "In their research, Zou and colleagues combined bioinformatics techniques with in vitro cellular studies to identify TIGD1 as a standalone prognostic indicator in colon cancer." (PMID 38651061, 2024). "The study suggests that TIGD1 accelerates the transition of cancer cells from the G1 to the S phase by triggering various colon cancer signaling pathways, such as Wnt/B-catenin, E-cadherin, N-cadherin, Bcl-2, BAX, CDK6, and cyclin D1." (PMID 38651061, 2024).
lung carcinoma (3 papers, 2024 to 2025). "Assessing OS risk scores showed a clear link between higher TIGD1 expression and reduced overall survival in lung cancer patients across different expression groups (p = 0.01)." (PMID 38651061, 2024). "This study elucidates the potential functions of TIGD1 in lung cancer and identifies promising biomarker candidates associated with TIGD1 gene expression, presenting potential therapeutic targets for lung cancer therapies." (PMID 39734333, 2024). "In conclusion, our findings suggest that TIGD1 holds significant potential as a diagnostic and prognostic marker in lung cancer, offering a promising target for the development of targeted therapies, including those based on immunotherapy and specific drugs." (PMID 38651061, 2024). "Given the involvement of the identified TIGD1-associated DEGs in pathways significant for the development of cancer cells, these DEGs show promise as potential biomarker candidates for lung cancer therapy." (PMID 39734333, 2024). "Their diverse roles in the intricate molecular machinery associated with TIGD1 expression provide a robust foundation for future investigations aimed at unraveling the complexities of lung cancer progression and developing effective therapeutic strategies." (PMID 39734333, 2024). "Our comprehensive analysis delving into the intricate molecular landscape associated with TIGD1 expression in lung cancer has revealed significant findings." (PMID 39734333, 2024). "In summary, the genes associated with TIGD1 function may serve as key players in the development of lung cancer and show potential as targets for lung cancer-targeted therapies." (PMID 39734333, 2024). "Preliminary studies have reported TIGD1 overexpression in colorectal, gastric, and lung cancers, where it correlates with poor prognosis and increased immune cell infiltration." (PMID 40565566, 2025). "These would strengthen the scientific basis for exploring TIGD1 as a potential biomarker and therapeutic target in lung cancer research." (PMID 39734333, 2024). "The GSE229260 microarray dataset was investigated using the GEO2R tool to identify the differentially expressed genes (DEGs) in TIGD1 silenced in A549 lung cancer cells in contrast to controls." (PMID 39734333, 2024). "Bioinformatics analysis revealed TIGD1’s potential as a biomarker for diagnosing and predicting lung cancer." (PMID 38651061, 2024). "Through these investigations, potential proteins interacting with TIGD1 and molecular pathways elucidating the functional role of the TIGD1 gene in lung cancer were determined." (PMID 39734333, 2024). "The GSE229260 dataset, obtained from the Gene Expression Omnibus (GEO) database, includes data where TIGD1 was silenced using specific small-hairpin RNA (shRNA) in A549 lung cancer cells, a cell line representative of the NSCLC subtype." (PMID 39734333, 2024). "This dataset illustrates the functional role of TIGD1 in lung cancer by analyzing the expression pattern changes resulting from TIGD1 knockdown using the Human Gene Expression Array." (PMID 39734333, 2024). "Compared with normal tissues, significantly higher expression of TIGD1 was found in human lung cancer tissues (p < 0.001)." (PMID 38651061, 2024). "And it was found that the expression of TIGD1 is significantly increased in patients with high-grade lung cancer (p < 0.001)." (PMID 38651061, 2024). "Likewise, the level of TIGD1 expression in lung cancer cells was observed to be significantly elevated compared to that in normal cells." (PMID 38651061, 2024). "Notably, TIGD1 expression was found to be elevated in lung cancer tissues compared to normal counterparts, particularly in patients with advanced-stage lung cancer and lymph node metastasis." (PMID 38651061, 2024).
lung carcinoma (continued). "Understanding TIGD1’s precise regulatory mechanisms could reveal new therapeutic targets and strategies for lung cancer treatment, emphasizing the need for further studies to validate these findings in diverse models and clinical settings." (PMID 39734333, 2024). "Furthermore, Western blot analysis verified a significant increase in TIGD1 protein expression in both lung cancer cells and tumor tissues, in contrast to normal cells and neighboring non-tumorous tissues." (PMID 38651061, 2024). "However, the role of TIGD1 in lung cancer, especially in non-small cell lung cancer, has not been extensively explored in prior research." (PMID 38651061, 2024).
ovarian carcinoma (3 papers, 2021 to 2025). A malignant neoplasm originating from the surface ovarian epithelium. "Moreover, the response of ovarian cancer to platinum-based chemotherapy has been linked to TIGD1." (PMID 34858497, 2021). "In previous studies on ovarian cancer, it was observed that TIGD1 had an impact on the response of ovarian cancer patients to platinum-based chemotherapy." (PMID 38651061, 2024).
oral squamous cell carcinoma (2 papers, 2023 to 2024). "For example, in the study of oral squamous cell carcinoma, researchers found that TIGD1 regulates dendritic cell activity by activating the IL-17 signaling pathway, thereby promoting the occurrence and progression of oral squamous cell carcinoma." (PMID 38651061, 2024).
acute lymphoblastic leukemia (1 paper, 2025). Leukemia with an acute onset, characterized by the presence of lymphoblasts in the bone marrow and the peripheral blood. "Additionally, a noteworthy positive correlation between TIGD1 and inflammation was observed in both RB and acute lymphoblastic leukemia (ALL)." (PMID 40565566, 2025).
acute myeloid leukemia (1 paper, 2025). Acute myeloid leukemia (AML) is a group of neoplasms arising from precursor cells committed to the myeloid cell-line differentiation. "Single-cell sequencing analysis revealed robust positive correlations between TIGD1 expression and both DNA damage and inflammation in acute myeloid leukemia (AML)." (PMID 40565566, 2025).
hepatocellular carcinoma (1 paper, 2021). A malignant tumor that arises from hepatocytes. "Of note, a number of genes that were reportedly co-expressed with TIGD1 in hepatocellular carcinoma—as determined by in silico analysis—could also be found among the hub genes associated with the risk score." (PMID 34858497, 2021).
kidney chromophobe carcinoma (1 paper, 2025). "Interestingly, contrasting downregulation was observed in kidney chromophobe carcinoma, thymoma, and thyroid carcinoma, suggesting a potential dual role of TIGD1, acting as an oncogene in certain cancers while exhibiting a tumor-suppressive function in others." (PMID 40565566, 2025).
liver cancer (1 paper, 2024). An epithelial or non-epithelial malignant neoplasm that arises from the liver. "It has been reported that the expression changes of TIGD1 are particularly significant during the occurrence of liver cancer, suggesting its potential involvement in the development of liver cancer." (PMID 38651061, 2024).
meningioma (1 paper, 2021). A generally slow growing tumor attached to the dura mater. "In turn, recurrent mutations in the TIGD1 gene were found across all cytogenetic subgroups of meningiomas including both NF2-mutated and wild-type tumors." (PMID 34868937, 2021). "Overall, WHO grade 1 meningiomas harbored numerous and heterogeneous genetic variants, which most frequently affected the NF2 (47%) gene and to a less extent the PNMA6A (22%), TIGD1 (16%), SMO (13%), PTEN (13%), CREG2 (9%), EEF1A1 (6%), POLR2A (6%), ARID1B (3%), and FAIM3 (3%) genes." (PMID 34868937, 2021). "Another four genes (PNMA6A, TIGD1, PTEN, and SMO) were found to be altered in >10% of all WHO grade 1 meningiomas investigated, while the remaining CREG2, EEF1A1, and POLR2A genes were recurrently altered in a minority (<10%) of cases." (PMID 34868937, 2021).
renal cell carcinoma (1 paper, 2025). "TIGD1 expression was linked to cell proliferation in AML and ALL, inflammation in AML, RB, and renal cell carcinoma (RCC), and DNA repair and damage pathways in RB and UM." (PMID 40565566, 2025).
retinoblastoma (1 paper, 2025). A malignant tumor that originates in the nuclear layer of the retina. "In contrast, in retinoblastoma (RB), TIGD1 demonstrated significant positive associations with angiogenesis and cellular differentiation." (PMID 40565566, 2025).
skin cutaneous melanoma (1 paper, 2025). "Similarly, disease-free survival analysis revealed TIGD1 as a risk factor in ACC, LIHC, COAD, COADREAD, and skin cutaneous melanoma, while a protective association was observed in GBMLGG and LGG." (PMID 40565566, 2025).
uveal melanoma (1 paper, 2025). A melanoma derived from melanocytes of the uveal tract. "In RB and uveal melanoma (UM), TIGD1 exhibited marked negative correlations with DNA repair and DNA damage pathways." (PMID 40565566, 2025).
tumor (7 papers, 2021 to 2025). "Our findings suggest that TIGD1 is significantly associated with immune subtypes (C1-C6) and tumor-infiltrating immune cells." (PMID 40565566, 2025). "Through advanced data analysis techniques, we uncovered a significant correlation between TIGD1 expression and key factors such as clinical characteristics, the immune microenvironment, tumor mutational burden (TMB), and drug sensitivity." (PMID 38651061, 2024). "Additionally, high TIGD1 expression correlated positively with tumor mutation burden in LUAD, KIPAN, and KIRC, as well as microsatellite instability in CESC, LUAD, and BRCA, indicating a potential role for TIGD1 in immune checkpoint blockade therapy response." (PMID 40565566, 2025). "Therefore, a comprehensive investigation is warranted to evaluate TIGD1 expression across diverse malignancies, assess its diagnostic and prognostic value, and elucidate its mechanistic role in tumor progression and therapeutic resistance." (PMID 40565566, 2025). "Those pathways are significant for proteins involved in cellular processes and the expression levels of them, suggesting alterations in cancer metabolism gene expression, which emphasizes the potential role of TIGD1 expression in tumor progression." (PMID 40565566, 2025). "Particularly noteworthy is the robust positive correlation between TIGD1 and HMGB1 expression across nearly all tumor types, along with significant associations with ICAM1, CCL5, and TNFRSF18 in the majority of cancers." (PMID 40565566, 2025). "Given that the tumor microenvironment plays a crucial role in cancer progression and response to therapy, we explored TIGD1’s immune interactions across cancers." (PMID 40565566, 2025). "Through an integrative approach, we aimed to elucidate the oncogenic or tumor-suppressive role of TIGD1 and its functional relevance in tumorigenesis, cancer progression, and therapeutic resistance." (PMID 40565566, 2025). "Dysregulated cytokine and chemokine signaling impact tumor progression, angiogenesis, and immune modulation, suggesting potential connections between TIGD1, cancer, and immune response." (PMID 40565566, 2025). "This study provides a comprehensive, pan-cancer perspective on TIGD1, offering insights into its role in tumor progression, immune interactions, and response to treatment." (PMID 40565566, 2025). "Mechanistic studies using in vitro and in vivo models are essential to uncover the precise pathways through which TIGD1 contributes to tumor progression, immune modulation, and drug resistance." (PMID 40565566, 2025). "Expression analysis revealed a significant upregulation of the TIGD1 gene in diverse cancers, including distinct tumor subtypes and pathological stages, implicating its potential involvement in tumorigenesis consistent with the literature." (PMID 40565566, 2025). "Given that TFH cells are critical for B cell activation and humoral immunity, their correlation with TIGD1 suggests an immunomodulatory role, potentially influencing tumor progression and immune evasion." (PMID 40565566, 2025). "Following the data integration, we examined the differential expression of TIGD1 between normal and tumor tissues." (PMID 38651061, 2024). "Triggered transposable element derivative 1 (TIGD1) exhibits significant overexpression in various tumor cells and tissues, suggesting its involvement in cancer progression." (PMID 38651061, 2024). "Exploring the immune microenvironment uncovered notable variations in stromal cell expression, immune cell levels, and tumor purity between high and low TIGD1 expression groups." (PMID 38651061, 2024). "In a study investigating the roles of TIGD1 in oral squamous cell carcinoma (OSCC), it was revealed that the expression of the gene is associated with tumor infiltration." (PMID 39734333, 2024). "The quantitative PCR (qPCR) results indicated a marked increase in TIGD1 expression in tumor tissues when contrasted with normal tissues." (PMID 38651061, 2024).
tumor (continued). "TIGD1 expression analysis indicated that in most tumor types, including LUSC, the expression level was elevated compared to that in control samples." (PMID 39734333, 2024). "For instance, the higher the expression of TIGD1, the more advanced the tumour stage and the more likely to lymph node metastasis and distant metastasis; while, tumour infiltration depth not significant." (PMID 37441804, 2023). "According to Eliseo’s report based on supervised support vector machine learning, the high expression of TIGD1, to a certain extent, affects the sensitivity of tumour cells to cisplatin and improves patient outcomes after chemotherapy." (PMID 37441804, 2023). "TIGD1 expression levels were remarkably different in tumor tissue and pericardial tissue." (PMID 37190215, 2023). "Additionally, TIGD1 exhibits significant associations with immune cell infiltration, specifically influencing the TFH/Tregs ratio, which may impact tumor immunotherapy efficacy by modulating the TME." (PMID 40565566, 2025). "We examined the transcriptional levels of key tumor-dependent genes (RUVBL1, GTF3C4, TIGD1, and TAF1A) between groups categorized by MYCN expression levels (low vs. high, n = 30 each) using Q-RT-PCR." (PMID 39175876, 2024). "TIGD1 levels correlated with key features of the tumor immune microenvironment, including immune checkpoint gene expression, TMB, and MSI, suggesting a role in modulating anti-tumor immunity." (PMID 40565566, 2025). "Additionally, the pathological staging analysis via GEPIA2.0 indicated that TIGD1 expression varied significantly across different cancer stages in ACC, COAD, KICH, LIHC, OV, and THCA, supporting its potential role in tumor progression." (PMID 40565566, 2025). "Additionally, ESTIMATE analysis demonstrated negative correlations between TIGD1 expression and immune microenvironment scores—stromal scores, immune scores, and estimate scores—in multiple cancers (33 out of 39 cancers), suggesting its role in tumor immunity regulation." (PMID 40565566, 2025).